HGF (hepatocyte growth factor)
Diseases named in the same sentence as HGF in open-access papers (continued):
Sharing a sentence is not in itself a finding about the gene and the disease.
melanoma (continued). "Altogether, these results suggest that growth factors, including HGF, do not substantially alter the effects of acute treatment of melanoma cells with inhibitors of the MAPK/ERK pathway, vemurafenib and trametinib." (PMID 30513872, 2018). "In a more recently published report, it has been demonstrated that the proliferation and phenotype of six BRAFV600E patient-derived melanoma cells were not detectably influenced by exogenous HGF." (PMID 30513872, 2018). "As shown in this study, the correlation between the expression and the HGF rescue effect in melanoma cells treated with vemurafenib was not high (r2 = 0.56)." (PMID 30513872, 2018). "Overexpression of HGF and c-MET in melanoma cells enhances cell protection from cell death, which was shown to be mediated by the activation of the MAPK/ERK and PI3K/AKT pathways, frequently modified in melanomas." (PMID 30513872, 2018). "While UV-induced melanomas of the HGF/SF strain failed to exhibit metastasis to lymph nodes or distal organs, robust metastatic activity was seen in HGF/SF × NME1/2+/− hybrids bearing large (500 mm3) melanomas on back skin." (PMID 28788083, 2017). "Cabozantinib potently inhibits HGF-induced migration and invasion of B16F10 melanoma cells." (PMID 28103611, 2017). "It has been demonstrated that serum level of HGF significantly correlates with the stage of melanoma, although patient evaluation did not provide unambiguous results to validate HGF as a biomarker for melanoma response to BRAF inhibitors." (PMID 28829835, 2017). "Thus, our results indicate a regulatory role of GH on expression of HGF, MET and ERBB3 in human melanoma cells." (PMID 28223541, 2017). "We have investigated the influence of three different growth factors, bFGF, EGF and HGF used either alone or in combination, on the response of V600EBRAF melanoma cell populations established from surgical specimens to vemurafenib and trametinib, targeting V600EBRAF and MEK1/2, respectively." (PMID 28829835, 2017). "In this review, we summarize how the HGF/SF transgenic mouse has been used to reveal metastasis-regulating activity of four different genes (CDK4R24C, survivin and NME1/NME2) in the context of UV-induced melanoma." (PMID 28788083, 2017). "In particular, the HGF/SF × NME1/2+/− hybrid exhibits a tropism of metastases (lymph node > lung > liver > bone, brain, etc.)that is nearly identical to that observed in human melanoma." (PMID 28788083, 2017). "Using immunohistochemistry analysis of melanoma biopsies, an improved response to BRAF and/or MEK inhibitor therapy was found in patients with no detectable stromal HGF expression, as compared with those expressing HGF." (PMID 28147313, 2017). "Interestingly, we observed consistent expression of GH transcript in the melanoma cells as well as marked modulation of the IGF receptors and binding proteins (IGF1R, IGF2R, IR, IGFBP2, IGFBP3) and the oncogenic HGF-MET mRNA, in response to excess GH or GHRKD." (PMID 28223541, 2017). "Melanomas that metastasized in the hybrid strain indeed contained significantly fewer apoptotic cells than matched, non-metastatic tumors from HGF/SF mice." (PMID 28788083, 2017). "In addition, constitutive expression of HGF/SF results in activation of the receptor tyrosine kinase and proto-oncogene MET, a growth-promoting autocrine loop characteristic of many human melanomas." (PMID 28788083, 2017). "The unique role of HGF/MET signaling in conferring resistance to MAPK pathway inhibitors in BRAF and NRAS mutant melanoma suggests that combination therapy with small-molecule MET inhibitors may provide additional benefit beyond BRAF and MEK inhibitors alone." (PMID 28147313, 2017). "Among various RTKs studied in melanoma cells to explore pathways responsible for uncontrolled survival and growth, MET has emerged as one of the topmost mediator of proliferation and invasiveness stimulated by the paracrine or autocrine HGF production." (PMID 28548075, 2014).
melanoma (continued). "Incidentally, Grb2 SH2 domain-binding antagonists were shown in vitro to block HGF-induced migration and invasion in MDCK epithelial cells, metastasis formation of melanoma and prostate cancer cells in vivo, and the motility of human SW620 CRC cells in wound-healing in vitro assays." (PMID 24708867, 2014). "Hemizygosity in the nm23-m1 and nm23-m2 genes conferred strong metastatic activity to primary melanomas induced by UVR on back skin in the HGF+ mouse strain without effect on primary tumor growth characteristics." (PMID 22699362, 2013). "In marked contrast, however, all melanomas arising on the back skin of HGF+ × [m1m2]+/− mice, independent of tumor size and growth rate, showed evidence of metastatic spread." (PMID 22699362, 2013). "The enhanced ability of HGF+ × [m1m2]+/−- derived melanoma cell lines to migrate autonomously (i.e. in the absence of exogenous chemoattractant) as single cells in scratch assays suggests a clue to the metastatic behavior of these tumors." (PMID 22699362, 2013). "In melanoma-bearing HGF+ mice, no microscopic evidence of pigmented micrometastases was evident in potential target organs for metastasis (data not shown)." (PMID 22699362, 2013). "Moreover, HGF was also found to induce resistance to sunitinib, ATE684 (a selective ALK inhibitor), vemurafenib (the BRAF inhibitor, in BRAF-mutant melanoma), and lapatinib (a dual HER2 and EGFR tyrosine kinase inhibitor)." (PMID 23533466, 2013). "Crossing of the nm23-h1/nm23-h2 knockout in hemizygous-null form ([m1m2]+/−) to a transgenic mouse strain (hepatocyte growth factor/scatter factor-overexpressing, or HGF+ strain) vulnerable to poorly-metastatic, UVR-induced melanomas resulted in UVR-induced melanomas with high metastatic potential." (PMID 22699362, 2013). "However, compound 5b was cytotoxic at 50 μM on HGF cells, indicating that it is not selective for melanoma." (PMID 40808346, 2025). "Moreover, CAF-secreted hepatocyte growth factor (HGF) or TGF-β1- stimulates downstream PI3K-AKT/MAPK/ERK/STAT pathways, thus leading to anti-EGFR, anti-BRAF chemoresistance in colon cancer, glioblastoma, melanoma, etc.." (PMID 38347575, 2024). "Hepatocyte growth factor (HGF), a dominant stimulator of epithelial cell division, and its receptor c-met may play an important role in the invasion, motility, proliferation and progression of melanoma." (PMID 33451139, 2021). "Of note, the activation of MET by HGF has been suggested as a potential mechanism of acquired tyrosine kinase inhibitor (TKI) resistance to gefitinib in epidermal growth factor receptor (EGFR)-mutant non-small cell lung cancer (NSCLC) and to vemurafenib itself in BRAF-mutant melanoma." (PMID 33553157, 2020). "Indeed, HGF expression was correlated with innate resistance to BRAF inhibition, and increased HGF plasma levels predicted worse overall survival (OS) and progression-free survival (PFS) in BRAF-mutant melanoma patients." (PMID 33553157, 2020). "Hepatocyte growth factor (HGF), via stimulation of its cognate receptor c-MET, and activation of the downstream effector components (MAPK, STAT, PI3K-AKT cascades and NF-κB), increases the survival, motility and proliferation of several cell types of cancer cells, including melanoma cells." (PMID 33276788, 2020). "Interestingly, CAF-derived HGF is also sufficient to induce RAF inhibitor resistance via the binding of its receptor MET and reactivation of the MAPK and PI3K/AKT signaling pathways in melanoma cells." (PMID 31106200, 2019). "In another study, approximately 22% of the hepatocyte growth factor/scatter factor (HGF/SF) transgenic mice developed spontaneous melanoma with a mean onset of 15 months, which does not reflect the human melanoma since they exhibited a different dermal morphology." (PMID 30544544, 2018).
melanoma (continued). "In another study, one out of seven melanoma cell lines could be rescued from vemurafenib-induced growth inhibition by either HGF or FGF, but none by EGF, and in other cell lines only ‘partial rescue’ was observed." (PMID 28829835, 2017). "In summary, these findings add significant and novel mechanistic insight into the potential role of HGF/MET signaling in mediating resistance to BRAF and MEK inhibitors and support the clinical evaluation of MET kinase inhibitors and HGF-neutralizing antibodies in melanoma." (PMID 28147313, 2017). "As such, the HGF/SF GEMM may better model the other 50% of human melanomas not expressing mutant BRAF." (PMID 28788083, 2017). "The oncogenic signaling loop of HGF/SF and MET is also not represented in other GEMM systems as they often utilize the BRAFV600E mutation, which is only present in 35–50% of human melanomas, to aid in the induction of melanomas." (PMID 28788083, 2017). "While Lezcano and colleagues'replication also detected the presence of HGF in human melanoma tumor cells and stromalcells with increased expression at disease progression, they did not identify astatistically significant correlation between HGF expression and clinical outcome." (PMID 25490933, 2014). "Moreover, correlation between cMET expression and HGF rescue in vemurafenib-treated BRAF-mutant melanoma cells was not high in this study (r2 = 0.56) suggesting that cMET contribution to microenvironment-mediated BRAF-inhibitor resistance remains to be clarified." (PMID 28829835, 2017). "Detailed comparisons of molecular signatures between non-metastatic melanomas of the HGF/SF strain with metastatic melanomas of HGF/SF hybrid crosses may provide an ideal discovery platform for the diagnostic and prognostic markers that are so acutely needed for management of melanoma patients." (PMID 28788083, 2017). "Thus, the conclusion that melanoma cells can grow without exogenously delivered growth factors bFGF, EGF and HGF might be true for most of melanoma cells." (PMID 28829835, 2017). "In conclusion, we provide evidence of an additive negative effect of IL-6, HGF, and MCP-2 on clinical response to single or combination ICI in advanced melanoma." (PMID 36007304, 2022). "Overall, our data provide further support for a role of HGF and MCP-2 as candidate biomarkers of response to ICI in advanced melanoma, while proposing an additive negative effect of these two cytokines, together with IL-6, on response rates." (PMID 36007304, 2022). "This suggests that growth factors, including HGF, are not necessary for BRAFV600E melanoma cell growth in vitro." (PMID 30513872, 2018). "EGF, HGF and FGF strongly antagonized the vemurafenib sensitivity only in some of V600EBRAF melanomas tested; HGF in 5, EGF in 3 and different FGFs in not more than 1 out of 8 melanoma cell lines." (PMID 28829835, 2017). "Alternatively, we assessed the same parameters while culturing melanoma cells in the medium lacking exogenous bFGF, EGF and HGF for about 4 months, leaving cells dependent exclusively on autocrine growth factor production." (PMID 28829835, 2017). "We conclude that the composition or lack of exogenous growth factors bFGF, EGF and HGF do not markedly influence viability and phenotype of V600EBRAF melanoma cells and their response to vemurafenib and trametinib in vitro." (PMID 28829835, 2017). "There was no influence of vemurafenib and trametinib on the HGF level in both, medium with and without exogenous HGF, as shown for DMBC21 melanoma cell population." (PMID 28829835, 2017). "We conclude that melanocytes in the HGF/SF transgenic mouse, particularly in the papillary dermis, are vulnerable to UVA which interacts with eumelanin but not phaeomelanin to induce melanoma." (PMID 24223113, 2013).
melanoma (continued). "We could show that while advanced-melanoma patients responding to targeted therapy were characterized by higher pretreatment MPO levels, the pretreatment MMP-9, HGF and IL-8 levels were similar in both responders and nonresponders." (PMID 38730718, 2024). "Patient-derived BRAFV600E melanoma cells could grow without serum and exogenous growth factors, FGF2, EGF (epidermal growth factor), and HGF (hepatocyte growth factor), for at least 4 months without substantial changes in viability and cell phenotype." (PMID 31167513, 2019). "Stimulation by hepatocyte growth factor (HGF) or adhesion to collagen type I enhanced cell proliferation and apoptosis resistance via MAPK and Akt signaling pathways in GD3+, but not GD3-, human melanoma N1 cells." (PMID 29773994, 2018). "Interestingly, comparable results were also obtained for melanoma cells grown without exogenous growth factors bFGF, EGF and HGF for a period as long as 4 months prior the drug treatment." (PMID 28829835, 2017). "Moreover, the HGF/SF model system revealed prototypical MSG activity for NME1 and/or NME2 for the first time in an in vivo setting of melanoma, with suppression of metastasis in the absence of an effect on primary tumor growth." (PMID 28788083, 2017). "However, in subsequent studies, IHC detection of stromal or tumor HGF in pre-therapy melanoma specimens failed to predict patient response to BRAF inhibitors; therefore, the power of HGF as a negative predictor of response to BRAF-targeted therapies needs to be further investigated." (PMID 36324182, 2022). "Neither the cell cycle nor the activity of pathways important for melanoma maintenance, such as MAPK-ERK, WNT (wingless/integrated)/β-catenin, and NF-κB (nuclear factor kappa B), were affected by the absence or presence of FGF2, HGF, and EGF used alone or in combination." (PMID 31167513, 2019).
lung carcinoma (194 papers, 2010 to 2025). "We also demonstrated that MET inhibitors can overcome HGF‐induced resistance to EGFR tyrosine kinase inhibitors (TKIs) in EGFR‐mutated lung cancer cell lines." (PMID 36416133, 2023). "In lung cancer, we and other groups reported that activation of HGF/MET causes resistance to EGFR‐TKIs and ALK‐TKIs in EGFR‐mutated NSCLC and ALK‐rearranged NSCLC, respectively." (PMID 36416133, 2023). "In an interesting report, curcumin inhibited HGF-driven EMT-associated changes in lung carcinoma cells." (PMID 36291760, 2022). "The Overexpression of HGF is linked to a poor prognosis of patients in many solid tumors, such as lung cancer, head and neck, gastrointestinal, breast, and cervical cancers." (PMID 35620271, 2022). "Here, we demonstrate that loss of HAI-1 leads to the increased expression of HGF mRNA in lung cancer samples, which likely links loss of HAI-1 expression to the observed loss in M1 polarized TAMs." (PMID 34185790, 2021). "FOXF1 has also been shown to contribute to the tumour-promoting properties of lung cancer-associated fibroblasts, including the production of hepatocyte growth factor and fibroblast growth factor-2, both of which promote tumour growth." (PMID 30624614, 2019). "HGF in the tumor microenvironment can be derived from either the tumor cells or the tumor-associated stromal cells, and in lung cancer is mainly produced by the mesenchymal cells in the stroma." (PMID 30134579, 2018). "Hepatocyte growth factor (HGF) overexpression is an important mechanism in acquired epidermal growth factor receptor (EGFR) kinase inhibitor gefitinib resistance in lung cancers with EGFR activating mutations." (PMID 29664235, 2018). "Although both MET gene amplification and HGF treatment has been shown to induce gefitinib resistance in lung cancers with EGFR mutations, ErbB3 transactivation is involved only in MET amplification but not in HGF-induced resistance." (PMID 26919104, 2016). "We show that in epithelial cells, including lung carcinoma cells, stimulated with HGF, TIAM1—a critical regulator of cadherin-associated adhesion— is rapidly targeted for proteasome-dependent degradation via HUWE1-mediated ubiquitylation." (PMID 25543140, 2015). "In patients, raised levels of circulating HGF are frequently seen and, together with over-expression of HGF receptor, it is an evil pair of proteins causing the progression of lung cancer." (PMID 26310485, 2015). "Wang and colleagues reported that cancer associated fibroblasts (CAFs) isolated from lung cancer tissue produces hepatocyte growth factor (HGF), which activates the c-Met pathway resulting in the invasion and metastasis of cancer cells." (PMID 26517671, 2015). "HGF (hepatocyte growth factor)/MET signaling pathway is associated with acquired resistance to EGFR inhibitors in EGFR mutant non–small cell lung cancers." (PMID 25221930, 2014). "For example, we and other researchers reported that HGF overexpression can exist together with gatekeeper EGFR-T790M mutation or Met gene amplification in EGFR mutant lung cancer with acquired resistance to EGFR-TKIs." (PMID 24386407, 2013). "More recently, MET amplification and activation via HGF/SF has also been implicated in resistance to EGFR inhibition in lung cancer." (PMID 21049054, 2010). "The MET exon 14 skipping mutation (named METex14Del) described in lung cancer leads to prolonged activation of signaling pathways and aberrant cell responses, but the link between HGF signaling and cell responses remains unclear." (PMID 41184222, 2025). "Moreover, GAB1 is associated with HGF-stimulated VEGF production in EGFR-mutant lung cancer cell lines." (PMID 37627207, 2023). "In summary, these findings demonstrated that HGF, as a downstream gene, may be implicated in miR-144-3p regulation of the development of lung cancer." (PMID 35568918, 2022).